CDK2 (cyclin dependent kinase 2)
Diseases named in the same sentence as CDK2 in open-access papers (continued):
Sharing a sentence is not in itself a finding about the gene and the disease.
colon carcinoma (continued). "CDK2 was identified as a direct target of curcumin in colon cancer cells, and germacrone induces G1 phase arrest, associated with a significant decrease in expression of cyclin D1 and CDK2 and elevated expression of p21." (PMID 29636777, 2018). "DFMO and Rosuvastatin reduced protein expressions of cell cycle marker Cdk2 dose-dependently in colon tumors compared to untreated colon tumors." (PMID 27841323, 2016). "For instance, a study demonstrated that hinokitiol, a tropolone-related natural compound, downregulated the expression of cyclin A, cyclin E and Cdk2 via activation of p21 in HCT116 human colon cancer cells." (PMID 27007366, 2016). "Curcumin inhibits cyclin-dependent kinase 2 (CDK2) activity in vitro and decrease the proliferation of colon cancer cells, indicating G1 cell cycle arrest in a dose-dependent manner." (PMID 27834913, 2016). "The expression of cyclin A2, CDK1 and CDK2 in colon cancer HT-29 cells was decreased upon the knockdown of ANO1." (PMID 27732935, 2016). "The result showed that relative firefly luciferase activity of reporter plasmids containing the CDK2 3’ UTR binding site was significantly inhibited in colon cancer cells transfected with miR-302s, indicating that miRs inhibits Cdk2 protein, but not CDK2 mRNA." (PMID 25970424, 2015). "Similar phenomenon were reported that reducing cyclin A/CDK2 and Cdc25C expressions lead to S phase arrest in human Lovo colon cancer cells." (PMID 22300067, 2012). "CDK2 inhibition reduces the viability of human colon cancer cells." (PMID 39997612, 2025). "Furthermore, treatment of colon cancer cells (Caco-2) with the CDK2 inhibitor Roscovitine significantly reduced Caco-2 cell proliferation and survival, which is consistent with our findings." (PMID 40699652, 2025). "In another study, NPTX1 could inhibit cell proliferation through down-regulating cyclin A2 and CDK2 expression in colon cancer." (PMID 38012562, 2023). "Thus, targeting CDK2 has been recognized as a potential therapeutic approach for colon cancer treatment." (PMID 35890189, 2022). "Notably, the total protein levels of c-Myc and CDK2 were reduced by fargesin treatment in colon cancer cells." (PMID 33669811, 2021). "To discover more effective and less toxic CDK inhibitors, we have used computer-aided strategy to discover two CDK2 inhibitors, Adapaline and Fluspirilene for liver cancer and colon cancer, a CDK4/6 inhibitor Rafoxanide for skin cancer but not very effective for HCC." (PMID 34335258, 2021). "Taken together, our results demonstrate that fargesin suppressed EGF-induced cell proliferation and cell transformation in premalignant cells and cell proliferation and colony growth of colon cancer cells by modulation of cell cycle regulators via CDK2/cyclin E/p21WAF1/Cip1 complex formation." (PMID 33669811, 2021). "We further found that fargesin-induced colony growth inhibition of colon cancer cells was mediated by suppression of the cyclin dependent kinase 2 (CDK2)/cyclin E signaling axis by upregulation of p21WAF1/Cip1, resulting in G1-phase cell cycle accumulation in a dose-dependent manner." (PMID 33669811, 2021). "Taken together, these results suggest that GSPT1 regulates CyclinD1, CDK4, and Cdk6 through GSK-3 β, and indirectly affects the expression of cyclinE and CDK2 through p21 and p27, thus regulating the transformation of colon cancer cells from the G1 phase to S phase and promoting tumor progression." (PMID 33819920, 2021). "In addition, curcumin has an effective sensitization effect and can induce G1 cell cycle arrest of colon cancer HCT116 cells through cyclin-dependent kinase 2 (CDK2) as a direct target, effectively inhibiting the proliferation of HCT116 cells." (PMID 33578780, 2021).
colon carcinoma (continued). "CDK2 has been proven to be involved in acquired 5-FU resistance in colon cancer, and that it could regulate the ABC transporter." (PMID 31504073, 2019). "For example, Zeestraten and colleagues identified that Cdk1 but not Cdk2 can predict distant-metastasis-free survival and cause-specific survival in stage II colon cancer." (PMID 25511643, 2014). "Interestingly, XNT treatment dose-dependently reduced CDK2 expression in the colon cancer cell HCT116, suggesting CDK2 may be indirectly involved for XNT to display its broad antiviral activity." (PMID 34829954, 2021). "Previous studies have shown that the lncRNA STEAP3-AS1 affects the expression of CDKN1C, CDK2, and CDK4 and histone H3 acetylation, which are involved in regulating cell cycle progression in colon cancer." (PMID 40665344, 2025). "The antitumor mechanisms of ICT include the downregulation of cyclin-dependent kinase 2 (CDK2), inducing cell cycle arrest in HCC, colon cancer, and prostate cancer." (PMID 39840041, 2024). "This study revealed that remimazolam promoted the cell-cycle progression and proliferation of HCT8 colon cancer cells by upregulating CDK1, PTTG1, CDC25C, CDK4, PLK1, PCNA, Ki67, RNASEH2B, FEN1, Cyclin D1,CD44 CDK2, CDKN3, CDC45, IQGAP3, and CDK6." (PMID 38725628, 2024). "In conclusion, our study demonstrated that AGA extract has potential to inhibit the proliferation, metastasis by inducing apoptosis and G1 phase arrest efficiency by inhibiting the CDK2, CDK6/CDK4 proteins in colon cancer cells." (PMID 36597025, 2023). "After GSPT1 was silenced in HCT116 colon cancer cells, the expression of CyclinD1, CDK4/6, cyclinE, CDK2, p21, and p27 was detected by Western blot." (PMID 33819920, 2021). "In contrast, CDK2 and cyclin E protein levels were dramatically decreased in WiDr, HCT8, and HCT116 colon cancer cells by fargesin treatment in a dose-dependent manner." (PMID 33669811, 2021). "The molecular mechanism studies suggest that CDK2/cyclin E and CDK4/cyclin D are involved in the inhibition of colon cancer cell proliferation by fargesin via p21WAF1/Cip1 and c-Myc, respectively." (PMID 33669811, 2021). "Effects of fadraciclib on CDK2 and CDK9 substrates were sustained to the end of the period tested (24 h) as was observed earlier in Colo205 colon cancer cells." (PMID 32645016, 2020). "Apoptosis was activated in human colon cancer cells by modifying the expressions of Bax, Bcl-2, XIAP, caspase-3, p21 and CDK2 proteins." (PMID 27628414, 2016). "Here we show that in colon cancer cells, despite identical downstream SMAD signaling, activin and TGFβ have opposing effects on the cdk2 inhibitor p21 resulting in distinct regulations of each pathway." (PMID 22761777, 2012). "In detail, research has revealed that ginsenoside Rg3 disrupts the cell cycle at G0/G1 phase via the EGFR/Ras/Raf/MEK/ERK pathway in lung cancer (A549), liver cancer (Hep G2) cells, and the formation of Cyclin D1, CDK2, and CDK4 in colon cancer (SW620 and LoVo) cells." (PMID 40490812, 2025). "In addition, curcumin treatment leads to cell cycle arrest at the S or G2/M phase in colon cancer (MC38 and HCT 116) cells, accompanied by a reduction in the protein expression of cell cycle-related markers (e.g., cyclin A2, cyclin E1, CDK2, and p21)." (PMID 40490812, 2025). "Analysis of dataset GSE29623, an mRNA and microRNA profile in colon cancer, supported that miR-622 positively correlated with signature genes in cell cycle pathway, such as CDC6 (r = 0.421), CDK2 (r = 0.336), CCNE1 (r = 0.423), CCNA2 (r = 0.412), CCNA5 (r = 0.350), and MCM10 (r = 0.423)." (PMID 38166756, 2024). "Despite the initial setbacks that CDK2 inhibition by anti-CDK2 shRNA, antisense oligonucleotides, a dominant-negative CDK2, or overexpression of p27Kip1 failed to arrest the proliferation of colon carcinoma cells." (PMID 33805800, 2021).
colon carcinoma (continued). "In another study, geldanamycin was found to inhibit cyclin E/CDK2 and CDK4 in human prostate (DU145) and human colorectal (HT29) cancer cell lines, and it showed synergistic activity with the CDK 4/6 inhibitor (palbociclib) in HCT116 colon cancer cells." (PMID 33050377, 2020). "For example, colon cancer cells proliferate in the absence of CDK2 efficiently, whereas knockdown of CDK2 in osteosarcoma cells prevents their proliferation." (PMID 30389712, 2018). "To identify targets through which Cdk2 executes its functions in DNA damage responses, we labeled proteins in whole-cell extracts of wild-type RPE-hTERT and HCT116 human colon carcinoma cells with purified Cdk2as/cyclin A and the analog substrate [γ-32P]N6-(benzyl)-ATP." (PMID 22927831, 2012). "Moreover, in cell lines derived from oral squamous cell carcinoma (HSC-2, HSC-3, and HSC-4) and colon carcinoma (DLD-1), α-mangostin induced G1 arrest by downregulating CDK4, CDK2, cyclin D3, and cyclin E, as well as through the upregulation of the p27kip1 and p21waf1/cip1 CDK inhibitors." (PMID 34885809, 2021). "Taken together, these results suggest that fargesin induced complex formation of p21WAF1/Cip1/CDK2/cyclin E, resulting in impairment of the G1/S cell cycle transition and inhibition of cell proliferation of premalignant JB6 Cl41 and HaCaT cells, as well as WiDr, HCT8, and HCT116 colon cancer cells." (PMID 33669811, 2021). "In fact, the expression level of E2F2 was very low level in colon cancer and E2F2 inhibition could enhance proliferation and cell cycle of colon cancer cells by suppressing the expression of surviving and regulating the expression of C-MYC, CCNA2, MCM4 as well as CDK2." (PMID 32117628, 2020). "In this context, it is not surprising to observe that expression of CDK1, CDK2, and cyclin B2 (CCNB2), which have close functional interactions with an oncogenic protein CKS1B, was significantly increased in colon cancer samples in the TCGA data set." (PMID 31717435, 2019).
lung carcinoma (85 papers, 2008 to 2026). "In cellular component associations with lung cancer, the targets were mainly found in the cell projection membrane, cell periphery, plasma membrane, catalytic complex, and cyclin E1-cyclin-dependent kinase 2 (CDK2) complex." (PMID 39518920, 2024). "Polygalacin D reduces the expression level of CDK2 protein, further slowing down the progression and metastatic risk of lung cancer A549." (PMID 38245694, 2024). "Inappropriate expression of CDK2 has been implicated in various malignancies including lung carcinoma, pancreatic carcinoma, ovarian carcinoma, and sarcomas." (PMID 31223310, 2019). "Moreover, the p21/CDK2 complexes were found to be increased in parkin siRNA-treated lung cancer cells, and this increased association was correlated to the sub G0/G1 arrest in parkin siRNA-treated lung cancer cells." (PMID 31112565, 2019). "CDK2 inhibition disrupts centrosome clustering, triggering anaphase catastrophe in aneuploid lung cancers." (PMID 40232858, 2025). "Time-lapse fluorescence microscopy of fluorescent ubiquitination-based cell cycle indicator (FUCCI) cell cycle probes transduced into aneuploid lung cancer cells revealed distinct fates of bipolar and polyploid cells after CDK2 inhibition." (PMID 40232858, 2025). "The findings presented here indicate that, despite CDK2 antagonism of cultured or in vivo lung cancer PDXs, there exists a residual population of aneuploid cancer cells that continue to proliferate and resist apoptosis." (PMID 40232858, 2025). "Other DEPs including aldo-keto reductase family 1 member B1 (AKR1B1), cyclin-dependent kinase 2 (CDK2), death associate protein kinase-1 (DAPK1), peroxiredoxin-1 (PRDX1) and aldehyde dehydrogenase mitochondrial (ALDH2) are associated with lung cancer." (PMID 40088196, 2025). "Another significant circRNA is circRNA forkhead box O3 (circFOXO3), which has been shown to bind to cyclin-dependent kinase 2 (CDK2) and p21, and affect cell cycle regulation and apoptosis in breast and lung cancer." (PMID 41281941, 2025). "The CDK2/9 inhibitor CYC065 (where CDK2 > CDK9) treatment increased multipolar mitosis in lung cancer PDXs." (PMID 40232858, 2025). "RNA-Seq analyses after CDK2 inhibition of 4N versus 2N lung cancer cells were enriched for CDK1 pathway and KIF family members." (PMID 40232858, 2025). "These polyploid cancer cells persisted and proliferated despite CDK2 antagonism and contributed to the appearance of multinucleated cells that were detected in cultured lung cancer cells as well as in CYC065-treated PDX tumors transplanted into recipient mice." (PMID 40232858, 2025). "CDK2 displayed a strong binding affinity with multiple hydrogen bonds, salt bridges, and pi-pi stacking interactions, suggesting its potential as a drug candidate against CDK2 in lung cancer." (PMID 38905286, 2024). "CDK2 is a crucial protein involved in cell cycle regulation, and the dysregulation of the cell cycle is common in lung cancer." (PMID 38905286, 2024). "CDK-2 inhibition led to anaphase apoptosis and further inhibited the growth of lung cancer xenografts." (PMID 38184514, 2024). "In this study, we focus on four proteins that play crucial roles in the context of lung cancer: human cyclin-dependent kinase-2 (CDK2), SRC-2 domains of C-ABL, epidermal growth factor (EGF), and insulin-like growth factor-1 receptor kinase (IGF-1R)." (PMID 38905286, 2024). "In our comprehensive study, we conducted molecular modelling analyses to identify potential drug candidates for targeting four key proteins involved in lung cancer: CDK2, SRC-2 domains of C-ABL, EGFR, and IGF-1R kinase." (PMID 38905286, 2024). "CDK2 can become overactive, leading to uncontrolled cell division and tumour growth in lung cancer patients." (PMID 38905286, 2024).
lung carcinoma (continued). "In this study, after reducing RACGAP1 expression in lung cancer cells A549 and H1975 by using si technique, flow cytometry revealed that the expression of cell cycle-related proteins CDK2 and CDK4 was reduced." (PMID 38167018, 2024). "CDK2/9 inhibitor (CYC065)-treatment caused chromosome rings or multipolar mitoses to form in human (A549 and HOP62) and murine (LKR13 and ED1) lung cancer cells." (PMID 38031910, 2023). "Engineered over-expression of CDK2 or CDK9 was independently achieved by transient transfection of these respective expression plasmids within studied lung cancer cells, as confirmed by immunoblot assays." (PMID 38031910, 2023). "Immunofluorescent assays were performed in these CDK2 or CDK9 knocked-down lung cancer cells versus control transfected siRNAs." (PMID 38031910, 2023). "Our findings indicate the effectiveness of dinactin against lung cancer cells (Lu99 and A549) by inducing G0/G1 cell cycle arrest through the downregulation of cyclins A, B, D3, and cdk2." (PMID 36551502, 2022). "Meanwhile, ectopic expression of P65 also rescued S phase blockage and expression of cell cycle-related genes including CDK2, Cyclin D1 and Cyclin E1, in addition to NF-κB target genes including IL-1β, IL-6 and TNFα in lung cancer cells overexpressing ZNF24." (PMID 36457047, 2022). "As HSP90AA1 and CDK2 were important in the cell cycle and pyrimidine metabolism, we had reason to believe that HSP90AA1 and CDK2 have a positive role in lung cancer proliferation." (PMID 35586682, 2022). "Treatment with the CDK2 inhibitor indisulam, which phenocopies genetic CDK2 inactivation, led to sustained senescence induction when combined with palbociclib in various cell lines and lung cancer xenografts." (PMID 36067171, 2022). "In H1299 lung cancer and endometrial cancer cell lines, garcinol application resulted in cell cycle arrest and a marked decrease in cyclin-dependent kinase 2 (CDK2) and cyclin-dependent kinase 4 (CDK4) expression." (PMID 33799504, 2021). "We previously demonstrated that pharmacologic and genetic ablation of cyclin-dependent kinase 2 (CDK2) leads to an event termed anaphase catastrophe in lung cancer cells, confirmed with live-cell imaging." (PMID 34611480, 2021). "In lung cancers, CDK2 levels were over-expressed in more than 90%, and CDK4/6 in more than 23% of the patient samples Therefore, a CDK 2/4/6 triple inhibitor will likely be more effective than CDK4/6 dual inhibitor in these cancers." (PMID 33579185, 2021). "Mechanistic studies showed that DMDD treatment induced G1/S cell cycle arrest by suppressing CCNE1, E2F1 and CDK2 and upregulating tumor suppressor gene p21 in lung cancer cells." (PMID 33613291, 2021). "While we previously reported that lung cancer cells undergo anaphase catastrophe when exposed to chemotherapy and CDK2 inhibitors, here we show that this pathway is also induced in neoplastic T-cells." (PMID 34611480, 2021). "For example, siRNA silencing of Cdk2 and Csf2t genes induced apoptosis of neuroblastoma cells and lung cancer cells, respectively." (PMID 34233649, 2021). "A previous study identified that MAPK-mediated activation of CDK2 keeps a check on RB activity and prevents progression of Kras-mutant lung cancers." (PMID 34309585, 2021). "ART restricted proliferation of lung cancer cells in the G0/G1 phase by decreasing Cyclin D1, Cyclin E, CDK2, and CDK4 expression." (PMID 33316936, 2020).